MMP9 (matrix metallopeptidase 9)
Diseases named in the same sentence as MMP9 in open-access papers (continued):
Sharing a sentence is not in itself a finding about the gene and the disease.
bronchiectasis (continued). "Several reports have demonstrated that the MMP-9/TIMP-1 ratio is associated with the development of some diseases in newborn infants, including bronchiectasis and lung infection." (PMID 33263620, 2020). "In sputum samples from bronchiectasis patients with high levels of active MMP-9 and NE activity, we detected SLPI cleavage fragments." (PMID 29892293, 2018). "It has been previously reported that there is an overexpression of MMP-9 in bronchiectatic airways in vivo and that MMP-9 levels are increased in exhaled breath condensate in children with bronchiectasis." (PMID 26126526, 2015). "The purpose of this study was to identify the levels of MMP-9, known to cause bronchial damage in chronic pulmonary illness, and SIRT-1, an anti-aging and anti-infective regulatory protein, in patients with bronchiectasis and to evaluate the importance of these biomarkers in diagnosis." (PMID 40290232, 2025). "The bronchiectasis group had higher serum MMP-9 values than the control group (p<0.001)." (PMID 40290232, 2025). "Furthermore, research is required to assess the changes in SIRT-1 and MMP-9 levels in other bronchiectasis phenotypes, such as inflammatory or infectious forms." (PMID 40290232, 2025). "When analyzed from a clinical standpoint, it might offer a fresh viewpoint on whether SIRT-1 and MMP-9 can be employed as biomarkers in bronchiectasis patients." (PMID 40290232, 2025). "The ROC analysis of study showed a high sensitivity of MMP-9 for the diagnosis of bronchiectasis." (PMID 40290232, 2025). "ROC analysis of MMP-9 in serum results that can predict bronchiectasis." (PMID 40290232, 2025). "Additionally, it was observed that MMP-9 had high sensitivity (93%) in the serum of patients with bronchiectasis." (PMID 40290232, 2025). "We might speculate that serum MMP-9 concentrations may help in the diagnosis of bronchiectasis given the with high precision." (PMID 40290232, 2025). "In addition, MMP-9 levels in BAL were found to correlate with the development of bronchiectasis in preschool children with CF supporting its role in early disease progression." (PMID 36362203, 2022). "In general, we speculate that the curative mechanisms of BMGLF in bronchiectasis are primarily associated with the expressional regulation of inflammatory factors such as IL6, IL10, MMP9, CXCL8, MAPK1, and ICAM1." (PMID 33488758, 2021). "In order to investigate if inclusion of these patients may affect our results, we repeated measurements of MMP-9 following exclusion of patients with bronchiectasis from both groups." (PMID 26126526, 2015). "In conclusion, in specific mucosal pathologies, such as bronchiectasis, neutrophils, and macrophage subsets control local immune reactions by proteolytic regulation, here described as the balance between MMPs (in particular MMP-9), serine proteases and local tissue inhibitors." (PMID 29892293, 2018). "This current study in bronchiectasis aimed to evaluate the role of SIRT-1, which may have a critical function in regulating inflammation and other pathophysiological pathways, and the neutrophil-derived protease MMP-9, which is known to cause bronchial damage in various lung diseases." (PMID 40290232, 2025). "For example, Tayloret al. found that increased levels of MMP-9, as well as MMP-8 and increased MMP:TIMP ratios, correlated with decreased lung function and higher levels of inflammatory markers in patients with bronchiectasis." (PMID 40174958, 2025). "This is the first study to examine serum MMP-9 and SIRT-1 levels together in individuals suffering from bronchiectasis." (PMID 40290232, 2025). "In patients with bronchiectasis, the presence of Rothia was found to be negatively correlated with pro-inflammatory factors such as IL-8, IL-1β, MMP-1, MMP-8, and MMP-9 in sputum." (PMID 38779669, 2024). "This study examined bronchiectasis SIRT-1 and MMP-9 levels and its relationship to age and gender." (PMID 40290232, 2025).
bronchiectasis (continued). "In the same study, whereas levels of MMP-8 and MMP-9 were increased in bronchiectasis, their primary inhibitor TIMP-1 was not, indicating a protease-antiprotease imbalance." (PMID 40174958, 2025). "However, we did not need to assess inflammatory marker levels since our goal was to evaluate MMP-9 and SIRT-1 levels, examine their levels among the patient control group, and determine their relevance in the diagnosis of bronchiectasis." (PMID 40290232, 2025). "In CF, the overexpression of MMPs (MMP-8, MMP-9 and MMP-12) correlates with the impairment of lung function; in particular, MMP-9 expression has been shown to correlate with RBM degradation, the onset of bronchiectasis and a decline of lung function in pwCF." (PMID 37569787, 2023). "In a cohort of adults with bronchiectasis, the abundance of Rothia species was negatively correlated with pro-inflammatory markers (interleukin (IL)-8 and IL-1β) and matrix metalloproteinase (MMP)-1, MMP-8 and MMP-9 in sputum." (PMID 36403054, 2022). "In CF patients with bronchiectasis, elevated MMP-9 levels have been reported compared to non-CF bronchiectasis patients and healthy controls." (PMID 26185365, 2015). "It was determined that MMP-9 might be reliable markers given their high sensitivity in the diagnosis of bronchiectasis, despite the fact that there was no discernible correlation between them." (PMID 40290232, 2025). "MMP-9 and SIRT-1 may be potential biomarkers in the diagnosis of bronchiectasis." (PMID 40290232, 2025). "Moreover, levels of VEGF, IL-8 and MMP-9 were significant lower as compared to non-PA patients, probably due to the diversity of PAstrains in bronchiectasis patients." (PMID 37118704, 2023). "We obtained very similar results since we found that MMP-9 was significantly increased in the BAL of AE-COPD patients as compared to stable COPD (p = 0.027), indicating inclusion of this small number of patients with bronchiectasis in both groups did not influence our results." (PMID 26126526, 2015).
chronic lymphocytic leukemia (20 papers, 2010 to 2025). "MMP-9 production in solid tumors has also been associated with increased metastasis, and in B-cell CLL levels of MMP-9 in plasma correlate with prognosis." (PMID 31919471, 2020). "The P6 peptide, FDAIAEIGNQLYLFKDGKYW, is a novel CD44-binding peptide that was identified from studying the interaction of pro matrix metalloproteinase-9 (pro-MMP-9) with CD44 as it relates to the proliferation of chronic lymphocytic leukemia (CLL) cells." (PMID 31877739, 2019). "On the other side, some studies indicated that CCR7/CCL21 interaction regulates MMP9 gene transcription by regulating Extracellular signal-related kinase (ERK)-effector c-Fos (AP1 complex) in B-cell chronic lymphocytic leukemia cell." (PMID 30781353, 2019). "In chronic lymphocytic leukaemia (CLL) cells, CD44, integrin α4 (also known as CD49d) and pro-MMP-9 are physically linked to CD38 in a supramolecular cell surface complex." (PMID 24713998, 2014). "Over-expression of angiogenic/invasive factors, including VEGF and MMP9, was found in patients with chronic lymphocytic leukemia (CLL), and microvessel count in tumor microenvironment was positively correlated to the clinical stage of these patients." (PMID 21559428, 2011). "Similarly, MMP-9 plays an important role in migration and survival, and speeds up the disease progression of chronic lymphocytic leukemias (CLL)." (PMID 32586313, 2020). "Matrix metalloproteinase-9 (MMP-9) contributes to chronic lymphocytic leukemia (CLL) pathology by regulating cell migration and preventing spontaneous apoptosis." (PMID 24956101, 2014). "In chronic lymphocytic leukemia (CLL), matrix metalloproteinase-9 (MMP-9) downregulates CD99." (PMID 40427525, 2025). "Matrix metalloproteinase-9 (MMP-9) facilitates the extravasation and lymphoid-tissue infiltration of chronic lymphocytic leukemia (CLL) cells." (PMID 40295829, 2025). "For example, it has been shown that non-catalytic functions of MMP-9 regulate STAT3 functions to drive survival in B-cell chronic lymphocytic leukemia (B-CLL) cells." (PMID 27158478, 2016). "In chronic lymphocytic leukaemia (CLL) CD44 is part of a surface molecular complex together with ⍺4β1, CD38, CXCR4, and MMP‐9 that is absent in normal B‐cells and coordinates adhesion and homing of CLL cells." (PMID 40690545, 2025).
colorectal tumor (20 papers, 2001 to 2024). "Analysis of MMP2 and MMP9 mRNA expression levels in eight primary colorectal tumours revealed a 3.6–13.7-fold increase in MMP2 (p = 0.0356) and a 0.5–320.7-fold increase in MMP9 (p = 0.5286) levels compared with healthy colon tissue." (PMID 35954423, 2022). "Numerous studies have demonstrated increased MMP2 and MMP9 mRNA, protein, and/or activity in colorectal tumor specimens compared to the normal colonic mucosa." (PMID 34830271, 2021). "MMP2 and MMP9 mRNA, protein, and/or activity have been found increased in colorectal tumor specimens compared to normal colonic mucosa." (PMID 34830271, 2021). "WNT3A was found to be overexpressed and correlated with the level of MMP9 in colorectal tumor tissues." (PMID 31850854, 2019). "The purpose of this study was to investigate the stability over time of MMP-9 in cryopreserved plasma, colorectal tumor tissue extract and macroscopically tumor-free colon mucosa tissue extract samples." (PMID 29520667, 2018). "Elevated expressions of MMP-3, MMP-9, and MMP-13 in colorectal tumors in Min/OPN(+/+) mice were decreased by OPN deficiency." (PMID 28505114, 2017). "In this context, MMP-9 is the main agent of cancer cell invasion and metastasis in the epithelial and stromal cells of the primary colorectal tumor." (PMID 24737953, 2014). "Furthermore, HMGA2‐siRNA delivery by CMD‐CS nanoparticles suppresses metastasis of colorectal tumor cells via down‐regulating MMP‐9 and vimentin, and upregulating E‐cadherin that are beneficial in enhancing DOX cytotoxicity." (PMID 36684100, 2023). "MMP9 was consistently upregulated in primary colorectal tumors." (PMID 35574354, 2022). "Although numerous studies have greatly improved the knowledge of colorectal tumor genesis, the association between parameters of chronic inflammation such as IL-6, C reactive protein (CRP) and MMP-9 is not fully understood as well as their relation to the progression of CRC." (PMID 30154846, 2018). "Studies have explored the hypothesis that the MMP-9 functions as a key regulator of the malignant phenotype in patients with colorectal tumors presenting with overexpression of this protease relative to the adjacent normal tissues." (PMID 24737953, 2014). "There was no increase in mRNA for MMP-9 or its specific inhibitor TIMP-1 in colorectal tumour tissue compared to normal, MMP-9 protein localized to the inflammatory infiltrate." (PMID 11401321, 2001). "Negative MMP-9 expression can predict poor prognosis in Dukes’ B colorectal tumours and may prove useful for identifying patients, who should be offered adjuvant treatment." (PMID 23216739, 2012). "MMP-3, MMP-9, MMP-13, MMP-2, and MMP-7 were upregulated in colorectal tumors in Min/OPN(+/+) compared to adjacent non-tumor parts." (PMID 28505114, 2017).
gastric ulcer (20 papers, 2010 to 2025). An ulcerated lesion in the mucosal surface of the stomach. "It has been suggested that MMP-9 levels and H. pylori infection were risk factors for gastric ulcer recurrence." (PMID 35163805, 2022). "The relationship between infection and expression of salivary miRNA in relationship to MMP-9 in patient with Helicobacter pylori-associated gastric ulcer was investigated in study 10 (“intermediate” quality)." (PMID 32019170, 2020). "Moreover, studies on single nucleotide polymorphisms (SNPs) of the MMP-9 gene revealed that the rs3918249-rs17576 CG haplotype increased the risk of H. pylori-positive PUD; SNPs in the MMP-9 gene were also associated with H. pylori-positive gastric ulcers (GU)." (PMID 39712025, 2024). "Patients with gastric ulcers reportedly exhibit increased MMP-9 production at the edge of the lesion." (PMID 36902320, 2023). "CUR prevented gastric ulceration and promoted the healing process by inhibiting MMP9 activity and enhancing MMP2 activity." (PMID 37513300, 2023). "In indomethacin-induced gastric ulcer in rats, ulcerated stomach extracts had an upregulation of 92 kDa pro-MMP9 activity and a moderate reduction in MMP2 activity." (PMID 37513300, 2023). "Specifically, authors investigated the effect of melatonin on the regulation of MMP-2 and MMP-9 in a rat model suffering from indomethacin-induced gastric ulcer." (PMID 35507858, 2022). "Our results are in agreement with the previous reports about more significant contribution of MMP-9 to the development of H. pylori-positive gastric ulcer and gastritis as compared to the other MMP genes." (PMID 34188075, 2021). "Significantly elevated expression of pro-MMP9 (about 12-fold) was documented in the indomethacin-induced gastric ulcer as compared to unaffected tissues." (PMID 34188075, 2021). "The cut-off point as 3.5 of MMP-9 over the inflammatory cells of the gastric ulcer lamina propria also achieved significant AUC as 0.69 (95% CI: 0.56–0.81, P = 0.007)." (PMID 22645431, 2012). "The significant elevation of the MMP9 level in gastric ulcer tissues suggested that the enzyme may regulate mucosa lesions in GU by degrading collagens and creating lesions." (PMID 34492072, 2021). "Researchers determined that ATL III inhibited 6% ethanol-induced PRGM cell death and cell membrane damage in rat gastric mucosa, and ATL III may have an anti-gastric ulcer effect by inhibiting MMP-2 and MMP-9 in a rat model of gastric ulcer induced by 70% ethanol." (PMID 37241729, 2023). "AT-III significantly and dose-dependently suppressed gastric ulcer formation via inhibiting matrix metalloproteinase (MMP)-2 and MMP-9 expression, decreasing the extracellular matrix (ECM) damage and preventing gastric ulcer formation." (PMID 38543015, 2024). "by working on 126 gastric ulcer patients showed that H. pylori-infected gastric ulcers had even higher MMP-7, MMP-9, and TIMP-1 expressions in epithelial cells compared to NSAID-related gastric ulcers." (PMID 35832384, 2022). "In the past 10 years, several animal studies with gastric ulcers have focused on the role of MMP-2 and MMP-9." (PMID 33233494, 2020). "Among the MMPs identified, MMP-9 is important in degradation of ECM and basement membrane barriers during gastric ulcer formation." (PMID 29523851, 2018). "The results show stronger patterns of MMP-9 and TIMP-1 expression in H. pylori-infected gastric ulcer tissues." (PMID 22645431, 2012). "Over superficial epithelium of gastric ulcer tissues, MMP-7, MMP-9, and TIMP-1 expressions were significantly lower in the NSAID-related group than in the H. pylori-infected group (P < 0.05)." (PMID 22645431, 2012). "H. pylori-infected gastric ulcers had even higher MMP-7, MMP-9, and TIMP-1 expressions in epithelial cells than NSAID-related gastric ulcers (P < 0.05)." (PMID 22645431, 2012).
gastric ulcer (continued). "In patients with the two combined factors, gastric ulcers expressed similar proportions of antral ulcers and MMP-7 and MMP-9 intensities to NSAID-related gastric ulcers, but lower MMP-9 and TIMP-1 than H. pylori-infected gastric ulcers (P < 0.05)." (PMID 22645431, 2012). "The findings indicate that H. pylori-infected gastric ulcers express higher MMP-7, MMP-9, and TIMP-1 compared to NSAID-related ulcers." (PMID 22645431, 2012). "Serum levels of MMP-9 (but not MMP-3 and MMP-7) were also higher in patients with H. pylori–associated gastric ulcer in comparison to those of patients with H. pylori–positive gastritis and cancer." (PMID 35163805, 2022). "Over inflammatory cells of the gastric ulcer lamina propria, only MMP-9 expression (not MMP-3 and TIMP-1) was significantly higher in the H. pylori-infected group than in the other two NSAID-use groups with or without H. pylori infection (P < 0.001)." (PMID 22645431, 2012). "It ameliorated the gastric ulcer caused by acetic acid by improving the expression of inflammatory genes such as COX-2, inhibiting negative remodeling promoted by MMP-9, increasing cell proliferation effect via EGF, and reducing cellular apoptosis by modulating caspase-3." (PMID 31979417, 2020). "Moreover, in the H. pylori-infected group, MMP-9 and TIMP-1 expressions over the superficial epithelium and MMP-9 expression over inflammatory cells of the lamina propria of gastric ulcer tissues were higher than in nonulcer tissues, respectively." (PMID 22645431, 2012). "MMP-3, MMP-9, and TIMP-1 expressions over inflammatory cells of the gastric ulcer lamina propria were also higher than in nonulcer tissues (P < 0.001)." (PMID 22645431, 2012). "MMP-7, MMP-9, and TIMP-1 expressions over the superficial epithelium of gastric ulcer tissues were higher than in nonulcer tissues (P < 0.05)." (PMID 22645431, 2012).